RXRB (retinoid X receptor beta)
Description:
Receptor for retinoic acid. Retinoic acid receptors bind as heterodimers to their target response elements in response to their ligands, all-trans or 9-cis retinoic acid, and regulate gene expression in various biological processes. The RAR/RXR heterodimers bind to the retinoic acid response elements (RARE).
Synonyms: NR2B2; H-2RIIBP; RCoR-1; RXRbeta; RXR-beta; DAUDI6
Tractability: Small molecule: an approved drug acts on it; a structure with a bound ligand is known; a high-quality ligand is known; it has a high-quality binding pocket; it belongs to a druggable protein family. PROTAC: ubiquitination databases record sites on it; its protein half-life has been measured; a small molecule that binds it is known.
Target class: Nuclear receptor; Nuclear hormone receptor subfamily 2; Nuclear hormone receptor subfamily 2 group B member 2; Nuclear hormone receptor subfamily 2 group B; Transcription factor
Chemical probes: JP3000, JP3000 (high quality)
Gene: Protein-coding gene on chromosome 6 (33,193,588 to 33,200,666, reverse strand). Ensembl gene ENSG00000204231.
Subcellular location: Nucleus; Cytoplasm
Subcellular location (Human Protein Atlas): Nucleoplasm; Cytosol; Nucleoli
Pathways (Reactome):
Signal Transduction: NR1H2 & NR1H3 regulate gene expression linked to gluconeogenesis; NR1H2 & NR1H3 regulate gene expression linked to lipogenesis; NR1H2 & NR1H3 regulate gene expression linked to triglyceride lipolysis in adipose; NR1H2 & NR1H3 regulate gene expression to control bile acid homeostasis; NR1H2 & NR1H3 regulate gene expression to limit cholesterol uptake; NR1H3 & NR1H2 regulate gene expression linked to cholesterol transport and efflux; Signaling by Retinoic Acid
Gene expression (Transcription): Nuclear Receptor transcription pathway
Metabolism: PPARA activates gene expression
Gene Ontology:
Molecular function: DNA-binding transcription activator activity, RNA polymerase II-specific; nuclear receptor activity; protein binding; RNA polymerase II transcription regulatory region sequence-specific DNA binding; sequence-specific double-stranded DNA binding; DNA-binding transcription factor activity, RNA polymerase II-specific; retinoic acid-responsive element binding; chromatin DNA binding; DNA binding; DNA-binding transcription factor activity; nuclear steroid receptor activity; sequence-specific DNA binding; transcription cis-regulatory region binding; zinc ion binding
Biological process: positive regulation of DNA-templated transcription; positive regulation of transcription by RNA polymerase II; cell differentiation; hormone-mediated signaling pathway; mRNA transcription by RNA polymerase II; nervous system development; positive regulation of bone mineralization; retinoic acid receptor signaling pathway; cellular response to retinoic acid; nuclear receptor-mediated steroid hormone signaling pathway; regulation of DNA-templated transcription
Cellular component: cytoplasm; cytosol; nucleolus; nucleoplasm; nucleus; RNA polymerase II transcription regulator complex; chromatin
Genetic constraint (gnomAD): Loss-of-function variants: 15 observed, 45.03 expected, observed/expected ratio (o/e) 0.33, 90% interval 0.22 to 0.51. The upper end of that interval is the gene's LOEUF score, 0.51, which puts it in group 2 of 6, group 1 being the genes least tolerant of losing a copy. Missense variants: 396 observed, 609.54 expected, observed/expected ratio (o/e) 0.65, 90% interval 0.6 to 0.71. Synonymous variants: 201 observed, 234.76 expected, observed/expected ratio (o/e) 0.86, 90% interval 0.76 to 0.96.
Homologues: Orthologues: chimpanzee RXRB (100% identical), macaque RXRB (100% identical), pig RXRB (99% identical), dog RXRB (98% identical), rabbit RXRB (98% identical), rat Rxrb (95% identical), guinea pig RXRB (76% identical), mouse Rxrb (76% identical), tropical clawed frog rxrb (66% identical), zebrafish rxrba (66% identical), zebrafish rxrbb (56% identical), Drosophila melanogaster usp (40% identical), and 26 more. Paralogues in human: RXRA (61% identical), RXRG (57% identical), NR2F1 (30% identical), NR2F2 (30% identical), HNF4G (29% identical), NR2F6 (28% identical), HNF4A (27% identical), NR2C1 (27% identical), NR2C2 (27% identical), NR2E3 (25% identical), NR2E1 (23% identical).
Diseases named in the same sentence as RXRB in open-access papers:
RXRB is named in the same sentence as 56 diseases in open-access papers, as found by Europe PMC text mining. Sharing a sentence is not in itself a finding about the gene and the disease. The quoted sentences say what the papers report.
breast carcinoma (5 papers, 2015 to 2025). "Used off-label for lung and breast cancer and Kaposi’s sarcoma, bexarotene binds to RXRs (RXRα, RXRβ, and RXRγ), activating these ligand-activated transcription factors to regulate gene expression." (PMID 40334012, 2025). "Steroid-Receptors, Heterodimeric-Receptors and the Lipid-sensors, Retinoid-X-Receptors (NR2B1/RXRα, NR2B2/RXRβ, NR2B3/RXRγ) are excluded from our analysis given the wealth of data on their therapeutic significance in breast-cancer." (PMID 26894976, 2016). "We have also shown that ATPR could induce apoptosis via RARβ/RXRβ heterodimers and activation of ER stress involving the MAPK pathway in the breast cancer MDA‐MB‐231 cells." (PMID 32391634, 2020).
esophageal squamous cell carcinoma (3 papers, 2005 to 2017). Esophageal squamous cell carcinoma (ESCC) is a type of esophageal carcinoma (EC) that can affect any part of the esophagus, but is usually located in the upper or middle third. "RXRB immunoreactivity and abnormal expression of RXRB mRNA have been disclosed to be associated with the status of lymph node metastasis in esophageal squamous cell carcinoma, and they may also be related to other carcinoma progressions." (PMID 24322297, 2014). "Therefore, the aim of the present study was to evaluate protein levels of retinoic acid receptors (i.e. RARα, β, γ, and RXRβ) in esophageal SCC and surrounding normal tissue of patients with untreated SCC and controls." (PMID 16277658, 2005). "Since little is known about the abundance of RARs and RXRs protein in esophageal SCC in humans, the major focus of the present study was to determine protein levels of RARα, β, γ, and RXRβ in normal, macroscopically unaffected esophageal tissue and SCC of patients with untreated SCC and controls." (PMID 16277658, 2005). "Protein levels of RARα, β, γ, and RXRβ were determined by Western Blot in normal esophageal tissue and tissue obtained from SCC of 21 patients with newly diagnosed esophageal SCC and normal esophageal tissue of 10 controls." (PMID 16277658, 2005).
melanoma (3 papers, 2019 to 2022). A malignant, usually aggressive tumor composed of atypical, neoplastic melanocytes. "Although, cytoplasmic expression of RXRβ was significantly reduced in human metastasis samples compared to the human melanoma samples indicating a role of RXRβ in mediating melanoma metastasis." (PMID 34692525, 2021).
schizophrenia (3 papers, 2016 to 2019). A major psychotic disorder characterized by abnormalities in the perception or expression of reality. "The decrease in RXRB in schizophrenia is interesting as the genetic locus of RXRB (6p21.3) has been linked to schizophrenia." (PMID 27992436, 2016). "This study presents evidence for down-regulation of the nuclear receptors NR4A1, NR4A2, RXRB, and KLF4 mRNAs in the DLPFC in schizophrenia and evidence of reduced RARG and RXRG expression in females with schizophrenia." (PMID 27992436, 2016). "This study reports significant changes in the nuclear receptors NR4A1, NR4A2, and RXRB and KLF4 in schizophrenia and provides further evidence of a role for the nuclear receptors in the disease process." (PMID 27992436, 2016). "A decrease in the level of RXRβ has already been correlated with schizophrenia, and RXR agonist—bexarotene—is currently in the third clinical trial phase for the reduction of positive symptoms of schizophrenia." (PMID 30402708, 2019).
small cell lung carcinoma (3 papers, 2018 to 2024). Small cell lung cancer (SCLC) is a highly aggressive malignant neoplasm, accounting for 10-15% of lung cancer cases, characterized byrapid growth, and early metastasis.
colon carcinoma (2 papers, 2015 to 2019). "Moreover, we found that RARα, RXRα, and RXRβ showed higher expression, while RARβ showed lower expression in colon carcinoma cells (poorly differentiated), the normal colon (highly differentiated) being the control (data not shown)." (PMID 25881300, 2015).
diabetes (2 papers, 2016 to 2021). "Treatment with GYY substantially mitigated the elevated expression of RXRα, RXRβ and RARγ1, suggesting an RXR and RAR regulatory role by GYY to mitigate PAI-1, MMP-9, MMP-13; thus, ECM turnover in diabetic kidney." (PMID 34680110, 2021).
gastric cancer (2 papers, 2023 to 2024). A primary or metastatic malignant neoplasm involving the stomach. "In fact, high levels of RARα, RARβ, RXRα and RXRβ are associated with unfavorable prognostic clinical and pathological characteristics of gastric cancer, such as stage-IV and “de novo” metastatic disease." (PMID 39323992, 2024). "In gastric cancer, high expression levels of RARα/RARβ/RARγ/RXRβ transcripts are associated with poor clinical and molecular characteristics as well as with reduced overall-survival." (PMID 39323992, 2024). "Finally, we established associations of the RARα, RARβ, RARγ and RXRβ levels with a detrimental effect on the overall-survival of gastric cancer patients." (PMID 39323992, 2024). "In this single-institution/retrospective clinical and translational study (RAR-GASTRIC), we define the expression of RARα, RARβ, RARγ, RXRα, RXRβ and RXRγ in stomach tumors with the use of archival tissue samples obtained from gastric cancer patients." (PMID 39323992, 2024). "Our data are consistent with the idea that RARα, RARβ, RARγ and RXRβ represent potential prognostic markers and therapeutic targets of gastric cancer." (PMID 39323992, 2024). "The results of the RAR-GASTRIC study demonstrate that gastric cancer specimens contain significant amounts of RARα/RARβ/RXRα/RXRβ mRNAs." (PMID 39323992, 2024). "Taken together, our data support the idea that the tumor levels of RARα, RARβ, RARγ and RXRβ mRNAs are potential determinants of a low overall-survival rate in gastric cancer." (PMID 39323992, 2024). "In this study, we determine the RNA expression of the six isoforms of Retinoic-Acid-Receptors (RARα/RARβ/RARγ/RXRα/RXRβ/RXRγ) in view of their potential use as gastric cancer progression markers and/or therapeutic targets." (PMID 39323992, 2024). "The work supports the idea that RARα, RARβ, RARγ and RXRβ represent potential prognostic markers and actionable therapeutic targets in the context of the personalized treatment of gastric cancer." (PMID 39323992, 2024). "To identify the RAR isoform(s) underlying the anti-proliferative action of the retinoid, initially, we evaluated the constitutive expression of RARα, RARβ, RARγ, RXRα, RXRβ and RXRγ mRNAs in our gastric-cancer cell-lines." (PMID 37951921, 2023). "Finally, we observe a worse overall-survival in gastric cancer patients characterized by high RARα/RARβ/RARγ/RXRβ mRNA levels." (PMID 39323992, 2024). "Based on our results, it is reasonable to assume that high expression levels of RARα, RARβ, RXRα and RXRβ have a negative impact on gastric cancer patients’ overall-survival." (PMID 39323992, 2024).
leukemia (2 papers, 2018 to 2024). A malignant (clonal) hematologic disorder, involving hematopoietic stem cells and characterized by the presence of primitive or atypical myeloid or lymphoid cells in the bone marrow and the blood. "In this study, we explored the relative expression levels of key transcription factors in leukemia cells by RT-qPCR, and the results showed that MYC, RXRB, were significantly up-regulated, while STAT1 expression was down-regulated in HAP1 compared to HS-5." (PMID 39465162, 2024).
lung carcinoma (2 papers, 2010 to 2024). "We found that the expression levels of RXRB in the tissues of patients with lung cancer were higher than those in the tissues of healthy people, suggesting its correlation with lung cancer." (PMID 38711144, 2024). "We compared the expression levels of RXRB in the tissues of patients with lung cancer and healthy people with the TCGA cohort (TCGA-LUAD/LUSC dataset)." (PMID 38711144, 2024).
Obesity (2 papers, 2015 to 2022). Accumulation of substantial excess body fat. "This raises the question as to which of the remaining 7/11 genes (LBP, RXRB, CPLX1, GLAK2, CSTL1, SLC9A3, CA12) may also have a role in obesity." (PMID 25651499, 2015).
pancreatic cancer (2 papers, 2024 to 2025). "Moreover, the expression of RARα and RXRβ is associated with higher OS in pancreatic cancer patients." (PMID 39850424, 2025). "The rest of the list expands to high expression of TRPV2 (Transient Receptor Potential Vanilloid 2) in cancerous skin cells, RXRB (Retinoid X Receptor Beta) in bone, and PPARG (Peroxisome Proliferator-Activated Receptor Gamma) in pancreatic cancer." (PMID 39766077, 2024).
vitamin A deficiency (2 papers, 2016 to 2022). Deficiency of vitamin A due to malnutrition, malabsorption, or dietary lack. "Vitamin A deficiency reduced the level of RXRβ mRNA, changed the rhythm amplitude of the PER1, REV-ERB genes and REV-ERB protein, and phase-shifted the daily peaks of RORα protein as well as BMAL1, RORα, RC3 and BDNF mRNA levels." (PMID 36466383, 2022).
adenoma (1 paper, 2005). A neoplasm arising from the epithelium. "Recently, in a study determining the role of RXR mRNA in Barett's esophagus mRNA levels of RXRβ were found to be higher in non-malignant tissue in patients with adenoma than in healthy controls." (PMID 16277658, 2005).
atherosclerosis (1 paper, 2022). A disease characterized by the build-up of fatty material and calcium deposition in the arterial wall resulting in partial or complete occlusion of the arterial lumen. "A novel function of retinoid X receptor beta (RXRβ) in endothelial cells has been reported by us during the formation of atherosclerosis." (PMID 35628577, 2022). "Therefore, our study uncovers a previously unknown ubiquitination pathway and suggests MDM2-mediated RXRβ ubiquitination as a new therapeutic target in atherosclerosis." (PMID 35628577, 2022). "Furthermore, the present study for the first time shows that pharmacological inhibition of MDM2 (which increased protein expression of RXRβ) attenuates the development of atherosclerosis and reverses mitochondrial damage and the related inflammation in this process." (PMID 35628577, 2022). "Moreover, the in vivo experiment in the present study for the first time showed that MDM2 inhibitor JNJ-165 alleviated the development of atherosclerosis and reversed mitochondrial damage and related inflammation in this process, along with the increased RXRβ protein expression in the aorta of mice." (PMID 35628577, 2022). "In this pathway, under conditions that lead to atherosclerosis, the expression of MDM2 is induced, and MDM2 functions as a ubiquitin E3 ligase to target RXRβ for degradation, which contributes to mitochondrial damage and subsequently mitochondrial-related inflammation in atherosclerosis." (PMID 35628577, 2022). "Therefore, based on our previous studies, we were encouraged to investigate whether MDM2 acts as an E3 ligase to regulate the stabilization of RXRβ and further illustrate the function of MDM2 in atherosclerosis." (PMID 35628577, 2022).
atrial fibrillation (1 paper, 2025). A disorder characterized by an electrocardiographic finding of a supraventricular arrhythmia characterized by the replacement of consistent P waves by rapid oscillations or fibrillatory waves that vary in size, shape and timing and are accompanied by an irregular ventricular response. "Mendelian randomization analyses suggest that genetic proxies for antidiabetic drug targets—KCNJ11/ABCC8, SLC5A2, and RXRB—reduce the risk of paroxysmal tachycardia (PT), right bundle branch block (RBBB), and atrial fibrillation (AF), respectively." (PMID 41357784, 2025).
bladder cancer (1 paper, 2022). "3.30.50.10.FF4220, a nuclear receptor family particularly likely to be free of side effects, contains proteins such as RXRA, RXRB and RXRG which show high expression in bladder cancer and are currently drug targets in other cancers (breast and prostate)." (PMID 35035776, 2022).
DiGeorge syndrome (1 paper, 2015). "Cell line analysis of genes altered by haploinsufficiency of RAI1 found retinoid x receptor beta (RXRB) as one of the ten main genes up-regulated and also proposed an interrelatedness in phenotype with several diseases that included DiGeorge syndrome and fragile X syndrome." (PMID 24519454, 2015).
eosinophilia (1 paper, 2010). "Postnatal skin-specific inactivation of both RXRα and RXRβ (RXRs) leads to the development of an AD-like disease characterized by partial hair loss, Th2 inflammation, eosinophilia, elevated TSLP epidermal secretion, and high TSLP serum levels." (PMID 20174635, 2010).
esophageal cancer (1 paper, 2017). A primary or metastatic malignant neoplasm involving the esophagus. "Five nucleoproteins MISP, KLF10, KLF15, PPP1R18, and RXRβ were identified by oligonucleotide trapping, as the binding factors on the TRE under TPA stimulation, and were expressed at varying expression levels in esophageal cancer." (PMID 29098164, 2017). "Several nucleoproteins (MISP, KLF10, KLF15, PPP1R18, and RXRβ) have been identified by affinity chromatography and mass spectrometry and could respond to TPA stimulation and regulate LCN2 expression in esophageal cancer cells." (PMID 29098164, 2017).
Hepatic steatosis (1 paper, 2022). Steatosis is a term used to denote lipid accumulation within hepatocytes. "Finally, LINC01260 was proposed as a key hepatic steatosis regulator, and its mechanism is probably related to the upregulation of RXRB expression as ceRNA." (PMID 35016686, 2022).
hepatocellular carcinoma (1 paper, 2022). A malignant tumor that arises from hepatocytes. "First, RXRB could bind to the promoter region of NR1H3 in HepG2 hepatocellular carcinoma cells." (PMID 35957896, 2022).
Hyperglycemia (1 paper, 2021). An increased concentration of glucose in the blood. "In summary, the present study demonstrates that in type-1 diabetic kidney, hyperglycemia results in the downregulation of PPARγ and the upregulation of RXRα, RXRβ and RARγ1, which possibly contributes to elevated PAI-1 levels, and thus, elevated MMP-9 and MMP-13." (PMID 34680110, 2021).
joint disease (1 paper, 2019). "Biological inference prioritized notable DMRs associated with skin disease (SIGLEC14, JAM3, PCOLCE, RXRB), skin and/or joint disease (MBP, OSBPL5, SNORD115, HCG26), and joint disease (IL22, ELF5, PPP2R2D, PTPRN2, HCG26)." (PMID 30779748, 2019). "Although few DMRs exceeded a 10% change in methylation, it is noteworthy that many of those which did play roles in the pathogenesis of skin disease (SIGLEC14, JAM3, PCOLCE, RXRB, ELF5, IL22), joint disease (MBP, HCG26, IL22, PPP2R2D, PTPRN2) or are known to be imprinted (OSBPL5, SNORD115)." (PMID 30779748, 2019).
memory impairment (1 paper, 2016). "These age-related memory impairments were associated with a hippocampal hypoexpression of RARα, RXRβ, and RXRγ mRNAs in middle-aged control animals." (PMID 27242514, 2016).